OCLN (occludin)
Diseases named in the same sentence as OCLN in open-access papers (continued):
Sharing a sentence is not in itself a finding about the gene and the disease.
infection (continued). "Whilst ablation of CD81, Claudin-1 and Occludin abolished infection for all four tested strains, a proportion of all strains was still able to infect SR-B1 knock-out cells." (PMID 33147126, 2021). "After infection with C. jejuni, HT-29/B6 cell monolayers showed a redistribution of barrier-maintaining occludin and claudin-5 off the TJ domain into intracellular compartments of the epithelial cells." (PMID 33935732, 2021). "At 10 d PI, OCLN mRNA levels were significantly affected by both infection (P = 0.029) and feed (P = 0.0009)." (PMID 33652244, 2021). "Similar to this, we previously observed a subcellular redistribution of the TJ proteins occludin, claudin-4 and claudin-5 as well as a disorganization of E-cadherin and F-actin in colonic mucosae from pigs infected with E. coli 536 at 5 h after infection." (PMID 34437391, 2021). "Relative mRNA levels of OCLN at 7 d PI was significantly affected by infection (P = 0.0079) with EM groups having lower OCLN levels than C groups." (PMID 33652244, 2021). "Results demonstrate that following infection with C. jejuni the addition of 0.25% Auraguard increased the expression of ZO-1 (p = 0.003) and occludin (p = 0.006) in cells." (PMID 34099034, 2021). "The early stage of PSaV infection also induced disruption of the TJs to reach the occludin coreceptor hidden beneath the TJ on the basolateral surface of polarized LLC-PK cells." (PMID 33692204, 2021). "Two-way analysis revealed that C. butyricum addition and NE infection at the same time affect the expression level of the protein OCLN, and the effect of interaction between C. butyricum and NE on OCLN expression was found to be significant (p < 0.01)." (PMID 34630156, 2021). "This pattern of apical localization was diminished upon infection with C. jejuni strain 81–176 and also resulted in an intracellular redistribution of occludin (insets, white arrows)." (PMID 32069333, 2020). "In this study, NE infection remarkably downregulated occludin and ZO-1 mRNA levels, while the NE-infected birds fed BLJ showed upregulated claudin-1 mRNA expression levels in the jejunum compared with those of untreated NE-infected birds." (PMID 32110391, 2020). "We also observed a significant increase in the expression of the TJ protein occludin in HT-29/B6-GR/MR cell monolayers after infection with C. concisus." (PMID 31936044, 2020). "In contrast, infection with wt C. jejuni or the wt complemented strain (ΔhtrA/htrAwt) led to the disruption of both occludin and claudin-8 in tight junctions along with their appearance in the cytoplasmic area (white arrows)." (PMID 33364202, 2020). "Occludin disruption was seen at 1 h post-infection corresponding with a more significant drop in TER (–14.0 ± 8.0%, change from baseline)." (PMID 31947656, 2020). "Consistent with our previous results, occludin remains at the cell borders at early time points after infection being displaced from the membrane at 60–120 min post-infection." (PMID 31947656, 2020). "After infection of T84 cells with wt C. jejuni, the fluorescence intensity of occludin and claudin-8 at the cell periphery was significantly reduced." (PMID 33364202, 2020). "Immunoblotting analysis showed that occludin and claudin 5 were downregulated 36 h and 24 h after infection, respectively." (PMID 32038167, 2020). "Recently, C. jejuni HtrA was shown to cleave E-cadherin and occludin upon infection of intestinal polarized Caco-2 cells." (PMID 33364202, 2020). "As expected, the infection resulted in an increase in the paracellular permeability of the intestinal epithelium, as well as a disorganization of occludin and ZO-1." (PMID 33379352, 2020). "In contrast, infection of T84 cells with wt C. jejuni or the wt complemented strain led to a significant drop of fluorescence intensity of occludin and claudin-8 in the cellular tight junctions." (PMID 33364202, 2020).
infection (continued). "The effects of C83901 infection and IL-17C on occludin protein expression were further confirmed by an immunofluorescence assay and Western blotting." (PMID 31221216, 2019). "The current study showed that intranasal PRV AH02LA infection down-regulated intestinal barrier genes expression in the ileum and colon, including Mucin-1, Mucin-2, and Occludin." (PMID 31195631, 2019). "Hyperphosphorylation of occludin, ZO-1, E-cadherin and β-catenin are detected on tyrosine residues during early infection; however, occludin and β-catenin are dephosphorylated on serine and threonine residues." (PMID 31681283, 2019). "Occludin transcription was significantly downregulated early during infection of the OE-129WT cells but slowly increased to a little over a 2-fold difference in gene expression levels versus the mock-infected cells at the 36hr time-point." (PMID 30625140, 2019). "Merged images showed the expression of MMP-9 and occludin at the same sites around the epithelium in the choroid plexus after infection with A. cantonensis." (PMID 31415587, 2019). "Occludin protein expression level and stability in OE-129WT cells remained steady throughout infection." (PMID 30625140, 2019). "There were significant increases in occludin and claudin-5 expressions in the meninges of the cerebrum and cerebellum in the second and third weeks after infection compared to the controls and those infected for 1 week." (PMID 30845271, 2019). "Exposure to OMVs or COF-SN from either EcN (white bars) or ECOR63 (grey bars) during infection counteracted the EPEC-induced downregulation of occludin and claudin-14, whose expression levels remained close to those of non-infected control cells." (PMID 31315566, 2019). "Occludin protein expression in the OE-TLR3(-) cells was significantly higher immediately after infection (8hr time-point) when compared the OE-129WT cells but slightly increased throughout the remainder of infection." (PMID 30625140, 2019). "Given the previous results, we conclude that PSaV first attaches to SAs on the apical cell surface, dissociates TJs, moves into the TJs, and then binds to occludin for successful entry and infection." (PMID 30463963, 2019). "Pronounced accumulation of occludin in the cytoplasm was evident, whereas ZO-1 remained in the paracellular junction area during early PSaV infection." (PMID 30463963, 2019). "The expressions of CSF tight junctional proteins claudin-5 and occludin in Western blot analysis tended to be higher 3 weeks after infection compared to the uninfected mice (p = 0.0286 and p = 0.057, respectively)." (PMID 30845271, 2019). "The E. faecium supplementation also tended to upregulate occludin mRNA expression 3 and 7 days post-infection (P = 0.053 and P = 0.051, respectively)." (PMID 29948799, 2019). "Four cell-surface molecules, CD81, occludin (OCLN), claudin 1 (CLDN1), and scavenger receptor class B member 1 (SRB1), are particularly important for HCV cell entry, although only CD81 and OCLN determine the species-specificity of infection." (PMID 29765366, 2018). "The most important TJ proteins in the intestinal mucosa are ZO-1, occludin, and claudins, and the expression of all 3 in the intestine are decreased by infection with ETEC K88." (PMID 30210262, 2018). "It is known that GS infection delocalizes the tight junctions claudin-1 and occludin in polarized Caco-2 cells but herein, we further show effects on amot (scaffolding protein) and mpp5 (PDZ protein that binds tight junction proteins, also known as Pals1)." (PMID 30062089, 2018). "HCV exploits several cell-surface molecules for cell entry, but only two of these (CD81 and OCLN) determine the species-specificity of infection." (PMID 29765366, 2018). "Similar effects were observed for occludin after infection of HIBCPP cells with E-30 Bastianni or 13-311." (PMID 29463289, 2018).
infection (continued). "Evaluation of the effects of H. pylori on cell monolayers, showed that after 24 h of infection, there was a decrease in the expression and/or membrane displacement of E-cadherin, occludin, and ZO-1." (PMID 30473688, 2018). "Expression of occludin was significantly reduced after infection with a correlating decrease in occluding RNA levels." (PMID 30401896, 2018). "Occludin depletion significantly elevated the levels of p24 in infected cultures by over 2-folds at day 2 and 3 and over 1.5-folds at days 5 and 7 post-infection." (PMID 29311803, 2017). "The results of the present study indicate that A. hydrophila significantly reduced the expression level of TJ protein occludin at 12 h post-infection (P < 0.05)." (PMID 28484272, 2017). "Infection with F4+ETEC caused TJ disruption, as indicated by ZO-1 and occludin delocalization from the membrane with scattered distribution of occludin inside the cells." (PMID 27688074, 2016). "The disruption of tight junctions, following the dissociation of the main structural component occludin, has been observed in bronchial epithelial cells following infection with B. cenocepacia and B. contaminans." (PMID 26636042, 2015). "Tight junction integrity and intact barrier function during infection were confirmed by occludin staining and maintenance of stable transepithelial electrical resistance (TER)." (PMID 24612002, 2014). "Based on the results of this comparative analysis, involvement of OCLN in facilitation of infection in T cell lines prone to naturally occurring virus was examined." (PMID 23626783, 2013). "OCLN, which is another member of the TJ protein family, was shown to mediate infection of Huh7.5 cells by HCVcc and to be likely involved at the later stages of HCV entry." (PMID 23626783, 2013). "The remaining antibodies targeting CD81, CLDN1, and OCLN all continued to strongly inhibit infection when added after the binding phase, indicating these factors are post-binding HCV cell entry factors." (PMID 23555257, 2013). "In immunocytochemistry, expression of G, F and M2-1 proteins after infection with RSV was markedly inhibited from 5 μg/ml curcumin, whereas upregulation of claudin-4 and occludin at the membranes after infection with RSV was inhibited by 10 μg/ml curcumin." (PMID 24058438, 2013). "Previous studies showed that enteric bacterial pathogens can directly modify TJ proteins, such as occludin, claudins, and ZO-1, or by alter the perijunctional actomyosin ring during invasion and infection." (PMID 23505542, 2013). "The upregulation of claudin-4 and occludin after infection with RSV was enhanced by 1 and 5 μg/ml curcumin and was prevented by 10 μg/ml curcumin." (PMID 24058438, 2013). "We found that antibodies targeting CD81, CLDN1, and the OCLN EC2-F5 mutant blocked infection when added either pre- or postbinding, indicating that these agents block postbinding HCV cell entry events." (PMID 23555257, 2013). "In caco-2 cells, the levels of TJ membrane proteins claudin-1 and occludin and also the adherens junction proteins β-catenin and E-cadherin was drastically reduced at day 2 post-infection whereas the effect was marginal on α-catenin." (PMID 23894488, 2013). "Transduction with lentiviruses expressing shRNA resistant wild type and EC2-F5 mutant OCLN restored infection with both these viruses." (PMID 23555257, 2013). "Infection with both meningococcal strains resulted in generating a weak lower-sized 50-kDa occludin fragment in infected HBMEC at 24 h p.i.." (PMID 20442866, 2010). "Silencing of OCLN expression lead to inhibition of HCVpp infection in Hep3B cells and inhibition of infection of both HCVpp and HCVcc in Huh-7.5 cells." (PMID 19643019, 2009). "Additionally, RhoA and ROCK inhibitors significantly reduced pMLC2 activation during early MVC infection, preventing TJ dissociation and partially restoring Occludin localization." (PMID 40142587, 2025).
infection (continued). "In addition, in vivo studies observed decreased OCLN and ZO-1 expression in chicken lungs post-infection with NDV." (PMID 40880512, 2025). "Occludin is a key sealing junction protein in the lung decreased by IV infection." (PMID 40733618, 2025). "Meanwhile, during the early stage of MVC infection, Occludin expression was upregulated." (PMID 40142587, 2025). "Our bullfrog model reproduced these hallmarks: IL-1β and IL-8 transcripts rose sharply then gradually declined as cytokine stores were exhausted, whereas the tight-junction proteins Claudin-7, ZO-2, and Occludin remained significantly down-regulated throughout infection." (PMID 40941293, 2025). "Control HC11 cells exhibited minimal delay in mitosis, with nearly all completing the process within 42 min, which curiously is slightly shorter than the prophase duration shown by the control cells in the OCLN experiment, presumably as a result of shRNA lentiviral infection." (PMID 38884279, 2024). "Moreover, immunofluorescence analysis was performed to examine the distribution and expression of ZO-1, Occludin, and Claudin-5 in Egr-1−/− and WT hBMEC upon infection." (PMID 38233877, 2024). "Infection with E. coli K99 markedly decreased ZO-1, occludin, and Claudin-1 expression." (PMID 39769422, 2024). "GPS infection significantly altered the distribution patterns of ZO-1 and Occludin." (PMID 38927100, 2024). "During early HIV invasion of the brain and interaction with the blood–brain barrier, there is a regulatory role for CtBP1 nuclear translocation by the brain pericyte tight junction protein occludin, with occludin levels decreasing by approximately 10% within 48h post-infection." (PMID 38932279, 2024). "The protein levels of tight junction-related proteins (ZO-1, occludin and claudin 3) reached their peak level at 4 hpi and then decreased, while those of the transcriptional regulators (p38, PKCα and p65) up-regulated and maintained high levels post-infection." (PMID 36768530, 2023). "In addition, the expression of p-p38 and p-p65 was decreased, and the expression of Occludin and Claudin-3 was increased after inhibition of calcium signalling during infection with S. maltophilia in MMECs." (PMID 38124149, 2023). "Consistently, we also found that ST infection dramatically reduced the expression of Occludin and Claudin-1, whereas LP postbiotics as well as the live probiotic could prevent the decrease, indicating their ability to enhance mucosal barrier." (PMID 37893938, 2023). "To determine if barrier properties might be altered following infection, we immunostained infected iBECs 72 h PI to detect TJ proteins Occludin, Claudin-5, and ZO-1." (PMID 37139492, 2023). "The occludin network pattern was found disrupted 24 hours post-infection." (PMID 38011105, 2023). "The expression of PILT (tight junction protein 4) significantly (p < 0.05) increased in the MOS groups upon infection and peaked at 4 or 24 hpi, while ZO-2 (zonula occludens 2) and occludin showed a higher expression in the MOS groups at 0 hpi and then decreased gradually post-infection (p > 0.05)." (PMID 36768530, 2023). "At 5 d PI, images revealed large areas of the infected iBEC monolayer with low or undetectable Occludin, Claudin-5, and ZO-1, despite a monolayer of adherent cells still present, indicating that the breakdown of TJs occurs with infection, potentially contributing to leakiness of the barrier." (PMID 37139492, 2023). "Furthermore, infection of 253G1 cells with HCV-JFH1-tau Lot B1 having M706L mutation was blocked by anti-CLDN6 antibody as well as anti-CD81 and anti-OCLN antibodies." (PMID 36424447, 2022). "The re-localization of occludin by astrovirus does not require productive infection; the viral capsid protein alone is sufficient to cause disruption in vivo and in vitro." (PMID 35452499, 2022). "There is a downward trend in occludin mRNA in BALB/c mice following infection." (PMID 36680154, 2022).
infection (continued). "However, during infection, only claudin-14 increased on both the mRNA and protein level, while occludin protein expression remained unchanged." (PMID 35821354, 2022). "Additionally, infection with HCV-JFH1-based HCVpp having M706L mutation, similar to that with wild-type HCV-JFH1-based HCVpp, showed a CD81-, SRBI-, and OCLN-dependent manner." (PMID 36424447, 2022). "Interestingly, expression of OCLN was increased in hCMEC/D3s with infection, and we observed a tendency towards upregulation of TJP1 and CLDN5 together with downregulation of SNAI1 after 8 h of N. meningitidis infection." (PMID 36289516, 2022). "In addition, oral GA markedly blocked the raised level of IκBα phosphorylation induced by ESBL-EAEC infection, and the suppression of occludin protein expression level was significantly blocked by GA pretreatment." (PMID 35399688, 2022). "This gene belongs to claudins’ family which are, with occludin proteins, tight junction proteins located at the apical side of piglet enterocytes and thus play a role in intestinal permeability and infection." (PMID 34349744, 2021). "ZO-1, claudin-5, and occludin decreased at the transcript and/ or protein level of brain endothelial cells after Group B Streptococcus, Neisseria meningitidis, Streptococcus suis, or E. coli infection." (PMID 34437417, 2021). "We used confocal microscopy to investigate the effects of equivalent infectious doses of HRV-16 (uses ICAM-1 receptor), HRV-1A (uses LDL receptor), and HRV-C15 (uses CDHR3 receptor) on tight junction organization (ZO-1 and occludin) at 24 h post infection in highly differentiated ALI cultures." (PMID 34135327, 2021). "In present study, we observed that the mRNA expression of occludin, ZO-1, and claudin-1 and protein expression of occludin was significantly lower in AA-ST group than that in AA group, which indicated that AA was helpful for infection/invasion of S. Typhimurium to TJ proteins in ileum." (PMID 34945541, 2021). "In the present study, higher concentrations of thymol nanoemulsion greatly upregulated genes encoding occludin, zona occludens-1, claudins -1, JAM, MUC-2 and FABP2 controlling the barrier functions even after experimental infection, and it was better than thymol." (PMID 33833292, 2021). "Consistently, we found a progressive loss of occludin staining on the bronchial epithelium during the infection and a near absence of staining in D9 samples." (PMID 32119672, 2020). "In addition to Zo-1, the Se-S mice showed an increase trend in occludin at day 9 PI, the start of the peak of infection, and also during the clearing phase of day 16 PI, compared to Se-D mice." (PMID 32775340, 2020). "Infection of S. aureus significantly degraded occludin, claudin-1, ZO-1 and JAM-1, and preincubation with L. fermentum NCU3087 or L. fermentum NCU3088 significantly attenuated degradation of these tight junction proteins, but still had a significant difference with the control group." (PMID 33042071, 2020). "In our model, a loss of permeability and TEER following E-30 infection was observed, which correlates with the diminution of barrier relevant membrane proteins in HIBCPP cells such as ZO-1 and Occludin, which connect the actin cytoskeleton to the cellular membrane." (PMID 33321840, 2020). "The results presented here suggest that claudin-8 is a major novel cleavage target for C. jejuni HtrA, and besides occludin, the second target protein in the tight junctions, which may help the pathogen to disrupt the epithelial barrier during infection." (PMID 33364202, 2020). "ETEC K88 was able to obviously decrease expression levels of ZO-1 and occludin in IPEC-J2 cells (P < 0.05) while L. salivarius involvement prior to infection had the capability to significantly increase the levels of these two tight junction proteins (P < 0.05)." (PMID 32774852, 2020).